TNF (tumor necrosis factor)
Diseases named in the same sentence as TNF in open-access papers (continued):
Sharing a sentence is not in itself a finding about the gene and the disease.
respiratory diseases (68 papers, 2009 to 2026). "Vitamin C and zinc modulate oxinflammation, combating reactive oxygen species and reducing the expression of TNF-α and IL-6, inflammatory cytokines associated with respiratory disease progression and PACS." (PMID 40161300, 2025). "TNF-α is a cytokine with pro-inflammatory properties that has a role in the inflammatory response and tissue damage associated with respiratory diseases." (PMID 38999876, 2024). "Both IL-18 and TNFα have been proposed as potential diagnostic and prognostic biomarker for the pathogenesis of respiratory disease." (PMID 37243736, 2023). "An association of TNF rs1800629 SNP with respiratory disease in NSAID-tolerant patients was also found." (PMID 35456412, 2022). "Of relevance to the environmental metals/metalloid under study here, TNF polymorphisms have also been associated with iAs-associated skin lesions and respiratory disease." (PMID 25479081, 2014). "TNF-α has been implicated as a key cytokine in many inflammatory disease conditions including respiratory diseases." (PMID 24386207, 2013). "It has been reported that disruption of the redox balance by CS leads to the production of proinflammatory cytokines, i.e., IL-1β, IL-6, IL-8, and TNFα in smokers, regulation of which is closely associated with the progression of respiratory diseases, such as COPD." (PMID 33660061, 2021). "Dynamic DORs induced by TNF-α stimulation showed statistically significant enrichment with inflammatory diseases, vascular diseases, and intestinal diseases and respiratory system disorders." (PMID 41085167, 2025). "The multifunctional inflammatory cytokine TNF-α, which is known for its capacity to stimulate the IL-1β and IL-6 release, emerges as a pivotal player in the pathogenesis of respiratory disorders within lung injury models." (PMID 39596850, 2024). "Pro-inflammatory cytokines, such as IL-1β, TNF-α, and IL-6, were quantified in the serum due to their crucial roles in initiating and sustaining inflammatory responses, particularly in respiratory disorders." (PMID 39596850, 2024). "Previous studies from our lab demonstrated that TNFα exposure increases metabolic demand in hASM cells consistent with airway hyper-contractility found in many respiratory diseases." (PMID 36982859, 2023). "Comparing patients with respiratory diseases and NSAID tolerance and controls, a statistically significant association was only found in the TNF rs1800629 SNP." (PMID 35456412, 2022). "For example, tumor necrosis factor α (TNF-α) has been implicated in post-transcriptional and/or translational upregulation of adhesion molecules and inflammatory genes in respiratory diseases." (PMID 31952230, 2020). "Proinflammatory cytokines, like TNF-α, IL-1β, and IL-6, by neutrophils are produced, which have close links with respiratory diseases." (PMID 29483931, 2018). "Elevated TNF-α and IL-6 levels can contribute to virus-mediated respiratory diseases or acute lung injury." (PMID 30105014, 2018). "Serum levels of IL-6, VEGF and TNF-a were significantly different between participants with active TB disease and those with other respiratory diseases." (PMID 28859607, 2017). "Experimental exposure of pigs to LPS following porcine respiratory coronavirus (PRCV) infection has led to more severe respiratory disease and increased TNF-α and IL-1β levels." (PMID 29157279, 2017). "Increasing data suggest that azithromycin suppresses the production of inflammatory cytokines such as TNF-α, IL-1β, IL-6 and macrophage inflammatory protein 2 apart from the antibiotic effect not only in respiratory diseases but also in genital infections." (PMID 25174641, 2014). "This study confirms that the TCM compound MBFD significantly enhances average daily weight gain in calves, elevates serum immunoglobulin levels (IgG, IgM), and reduces both respiratory disease incidence and pro-inflammatory cytokine levels (IL-6, TNF-α, IL-1β)." (PMID 41234407, 2025).
respiratory diseases (continued). "Related to respiratory disease, factor B can be synthesized and secreted by alveolar type II pneumocytes, polymorphonuclear cells, and alveolar M1 macrophages and further induced by local or systemic IL-1, IL-6, TNF-α, and/or IFN-γ activity." (PMID 39346910, 2024). "Expression of TNFα has been positively correlated with severity of porcine respiratory disease." (PMID 36726139, 2023). "In addition, IL-6, IL-1β, and TNF-α are proinflammatory cytokines that participate in many inflammatory responses of the lung, and studies have shown that the abnormal expression of IL-6, IL-1β, and TNF-α is related to the pathogenesis of respiratory diseases." (PMID 34135982, 2021). "Various cytokines, such as IL2, IL4, IL6, IL8, and TNFα, and other inflammatory markers, such as intercellular adhesion molecule (ICAM) 1, soluble P-selectin, and CRP, have previously been associated with metal exposure or respiratory diseases." (PMID 25272992, 2014). "However, IChek can be used measure multiple additional cytokines and other immune proteins including, TNF-α, another pro-inflammatory cytokine that has been shown to be critical in the immune response and pathology of bovine respiratory disease and bovine TB29." (PMID 34446770, 2021). "Furthermore, the release of IL-8, IL-6 and TNF-α at the basolateral compartment simulate the release of inflammatory factors from the epithelium into the bloodstream observed in animal and human (childhood) respiratory diseases." (PMID 32747652, 2020). "However, TNF seems to also be involved in respiratory disease in NSAID-tolerant patients, suggesting that it could be implicated in the inflammatory mechanism underlying the respiratory disease." (PMID 35456412, 2022). "Among them, representative respiratory diseases-related targets included IL-6, IL-10, IL-1β, TNF-α, interferon (IFN)-γ, epidermal growth factor (EGF) and its receptor (EGFR), TNF-α, transforming growth factor (TGF)-β1, etc." (PMID 31530860, 2019). "The acute LPS challenge was used to model TNF-α and MIP-1β increase as well as neutrophilia, which are hallmarks of complex respiratory diseases including ALI/ARDS and COPD." (PMID 22952743, 2012). "The weighted mean difference of − 0.20 pg/mL in TNF-α is likely a small absolute change with questionable therapeutic consequences, given the absence of recognized MCID guidelines for inflammatory cytokines in respiratory disorders." (PMID 41555409, 2026). "Other candidates mainly include growth factors and cytokines, such as vascular endothelial growth factor (VEGF), Proteases, Interferon (IFN), SCFAs, Tumor Necrosis Factor (TNF), Tobacco particles and so on, which are closely related to IBD and respiratory diseases." (PMID 37680747, 2023). "Therefore, understanding the roles of IL-6, IL-13, IFN-γ, and TNF-α is essential for developing an effective vaccine and treatment against SARS-CoV-2 and other respiratory diseases." (PMID 38060612, 2023). "Tumour necrosis factor alpha (TNF-α), transforming growth factor-β (TGF-β), interleukin-1 (IL-1) and interleukin-6 (IL-6) are well-known biomarkers of proinflammatory cytokines, which have also been found to be increased in respiratory disease." (PMID 36367996, 2022). "Anti-TNF alpha therapy does not ameliorate disease in a model of acute virus-endotoxin mediated respiratory disease in pigs." (PMID 32256705, 2020). "TNF-α and IL-6 are the key contributors to IAV-mediated respiratory diseases and acute lung injury." (PMID 30105014, 2018). "Patients with respiratory disorders without CPA had also significantly higher values for IFN-γ, IL-1b, IL-6, IL-8, and TNF-α compared to healthy individuals." (PMID 30333797, 2018). "Levels of IL-1b, IL-6, IL-8, TNF-α, and IFN-γ were significantly higher in CPA patients compared to healthy individuals (p < 0.001 and p = 0.008, respectively), but not different than in patients with respiratory disorders without CPA." (PMID 30333797, 2018).
hematological malignancies (60 papers, 2006 to 2025). "By contrast with ACR-7 and ACR-9 (hematological disorder), TNF and HGF were significantly associated with ACR-6 (serositis), TNF negatively and HGF positively." (PMID 36858042, 2023). "TNF was positively associated with ACR-9 (hematological disorder) and ACR-10 (immunological disorder)." (PMID 36858042, 2023). "Altogether, TNF may play a crucial role in inflammation-induced hematopoiesis and may be implicated in the pathogenesis of some hematologic disorders." (PMID 34054827, 2021). "Although the malignancies reported in these trials are rare, comparing patients treated with anti-TNF therapies versus patients receiving methotrexate or no disease-modifying antirheumatic drugs suggested an increased risk of hematological malignancies in anti-TNF treated patients." (PMID 24151619, 2013). "The CD70-CD27 axis, a ligand-receptor pair in the tumor necrosis factor (TNF) superfamily, plays a crucial role in immune regulation and has been implicated in various hematological malignancies." (PMID 40205178, 2025). "Another prospective cohort study revealed that rheumatological patients, who received anti-TNF treatment, suffered more often from haematologic diseases than those who received, e.g., methotrexate." (PMID 40564114, 2025). "Further research is needed to evaluate risk factors for hematological malignancies in patients with IBD, particularly assessing the risks associated with anti-TNF therapy (infliximab) or vedolizumab when used alone or following treatment with thioprine." (PMID 39949431, 2025). "Risk factors for DH include patients with HIV disease, immunosuppressive therapies including steroids and TNF-blockers, hematologic malignancies, and transplant recipients." (PMID 39590675, 2024). "Another fact that favors the study of TNFα in hematologic malignancies is that TNFα concentration is higher in the serum of patients with progressive CLL compared to healthy donors or patients with indolent disease." (PMID 33540543, 2021). "It has been reported in only a small number of transplant recipients and in even fewer patients who have received tumor necrosis factor-alpha (TNF) inhibitors, or had hematological malignancies." (PMID 31323746, 2019). "Lastly, it is involved in the pathogenesis of solid tumors and hematological malignancies; (iii) TNF-α negatively regulates the expansion and self-renewal of HSPCs." (PMID 30116149, 2018). "We thus further subdivided the ImCo patients into two groups partly based on immunosuppression: Solid organ transplantation (SOT) and other immunosuppression (Other ImSupp) including the patients on anti-CD20 treatment, hematological malignities and TNF-α inhibitory treatment." (PMID 40431250, 2025). "While the true connection between individuals with hematological malignancies and PG requires further studies, this immune dysregulation and the inflammatory cytokine profile of tumor necrosis factor-alpha (TNF-α), IL-8, and vascular endothelial growth factor (VEGF) are suspected to be linked." (PMID 39165616, 2024). "AS patients treated with anti-TNF therapy showed no excessive risk for solid or hematologic malignancy." (PMID 37568555, 2023). "While LD can affect immunocompetent hosts, immunocompromised patients with solid tumors or hematological malignancies; solid organ transplants; or immunosuppressive medications such as tumor necrosis factor (TNF) inhibitors, corticosteroids, or antirejection medications are at increased risk." (PMID 37242396, 2023). "Anti-TNF-α have been involved in fatal blood disorders, infections, and liver injury." (PMID 25580435, 2014). "While the role of medical therapy, including thiopurines and Tumor Necrosis Factor (TNF)-α Inhibitors (TNFi), as a risk factor for hematological malignancy is supported by recent data, it remains unclear whether the disease itself poses a risk of developing these tumors." (PMID 37568640, 2023).
hematological malignancies (continued). "A total of 7 of the patients had undergone SOT (n = 7), and 12 of the patients had either hematological disease (n = 5), anti-CD20 medication (n = 6), or TNF-α inhibitor treatment (n = 1)." (PMID 40431250, 2025). "Spike stimulation increases IL-2 levels in patients with hematological malignancies, but the IFN-γ and tumor necrosis factor α (TNF-α) remain lower, which indicates a reduced magnitude of protection by T cell response." (PMID 36851363, 2023). "In parallel, TNF-alpha has been shown to be higher in patients with active disease, higher SLEDAI and hematological disease." (PMID 35620179, 2022). "Tumor Necrosis Factor alpha (TNF-α) protein is a major regulatory cytokine that plays a role in many immune-mediated diseases and hematologic malignancies." (PMID 26339619, 2015). "Likewise, increased levels of TNF-a, IL-8, and VEGF have been demonstrated in hematological diseases." (PMID 39165616, 2024). "Tear and serum TNF-α were significantly higher in the intended HSCT group at baseline compared to the control group, so these also may be elevated in hematologic disorders in general and would require validation as oGVHD-specific biomarkers." (PMID 33686249, 2021). "Hematological disorders, such as hemoglobin concentration, negatively correlated with TNF-α, IL-6, IL-27 and IL-10 (all p ≤0.0005); Platelet and eosinophil counts were negatively correlated with TNF-α, IL-6, IL-27 and IL-10 (p ≤0.0005)." (PMID 26814478, 2016).
peripheral neuropathy (56 papers, 2010 to 2025). A disorder affecting the peripheral nervous system. "The high risk of peripheral neuropathy and teratogenicity has limited thalidomide use, which has largely fallen out of favour with increased use of anti-TNF." (PMID 35268369, 2022). "Pain hypersensitivity associated with peripheral neuropathy was attenuated by the TNFα antagonist etanercept." (PMID 22189061, 2011). "It is hypothesized that BV may cause immune-mediated peripheral neuropathies, akin to those seen with TNF inhibitors." (PMID 40378127, 2025). "Clinical observations confirmed that cyclooxygenases and TNF-α participate in the peripheral mediation of neuropathic pain during chemotherapy, which produces peripheral neuropathy with massive release of this factor in serum." (PMID 39795254, 2025). "Because NAC prevents NF-kB activation, it suppresses the production of cytokines, including TNFα, IL-1β, and IL-2, which are important for the inflammatory pathway and the development of peripheral neuropathy." (PMID 41440136, 2025). "These variables showed that nearly 50% of the variation in the data, including pro-inflammatory IL-6, IL-17A, TNF-α, and LPS, contributed significantly to peripheral neuropathy." (PMID 41264657, 2025). "The ability of l-carnosine to protect against oxaliplatin-induced peripheral neuropathy has been partly attributed to the increased Nrf2 with its antioxidant machinery and the inhibition of both NF-κB and TNF-α." (PMID 36121569, 2023). "Paclitaxel-induced peripheral neuropathy (PN) is a consequence of activation of the inflammatory cascade with subsequent increased pro-inflammatory cytokine production including tumor necrosis factor-α (TNF-α), interleukin-1β (IL-1β), and interleukin-6 (IL-6)." (PMID 35596774, 2022). "For our in vivo model, biomaterial surgical implants containing TNF were used to induce peripheral neuropathy in rats." (PMID 36159399, 2022). "It has been shown that inflammatory cytokines such as IL-1β, IL-6, and TNF-α are involved in the progression of BTZ-induced peripheral neuropathy." (PMID 32733956, 2020). "As a therapeutic alternative to traditional anti-TNF-α compounds, we should pay more attention to its dose-related side effects, with the most notable being peripheral neuropathy." (PMID 32908940, 2020). "Recent studies have indicated that MAPK and NF-κB signaling contributed to PTX-induced peripheral neuropathy and increased expression of pro-inflammatory cytokines, such as IL-1β and TNF-α, within the DRG." (PMID 31024320, 2019). "Previous studies showed that oxaliplatin treatment causes astrocyte and glial cell activation and the production of TNF-α in a rat model of peripheral neuropathy." (PMID 30906773, 2019). "The currently available evidence shows that inflammatory cytokines, such as tumor necrosis factor alpha (TNF-α), interleukin-1 beta (IL-1β), and IL-6, which are secreted by immune cells contribute to the induction and progression of peripheral neuropathy." (PMID 32133063, 2019). "For example, the blockage of specific IL-1β and TNFα attenuated peripheral neuropathy in several animal models." (PMID 29963257, 2018). "The expression of cytokines and chemokines is a prominent feature of neuroinflammation and elevated levels of certain cytokines, such as TNFα, IL-6, and IL-1β, have been demonstrated in patients with painful peripheral neuropathies, such as GBS and CIDP34–39." (PMID 28811623, 2017). "The key role of pro-inflammatory mediators in the development of CIPN has found important confirmations in preclinical studies that proved the efficacy of specific IL-1β and TNFα blockage in attenuating peripheral neuropathy in relevant animal models." (PMID 28423567, 2017). "Spinal neuroinflammation in peripheral neuropathy is characterized by activation of microglia and astrocytes, as well as upregulation of the proinflammatory mediator, tumor necrosis factor-α (TNF-α)." (PMID 27541934, 2016).